IL15 (interleukin 15)
Diseases named in the same sentence as IL15 in open-access papers (continued):
Sharing a sentence is not in itself a finding about the gene and the disease.
Hypoalbuminemia (1 paper, 2021). The concentration of albumin in the blood circulation is below the lower limit of normal. "As we have outlined here, hypoalbuminemia and IL-15 may share a common pathophysiological mechanism mediated by the cytokine storm, which in turn appears to favor vascular permeability and neutrophil infiltration and leads to increased mortality risk." (PMID 34683480, 2021).
inflammatory breast carcinoma (1 paper, 2025). An advanced, invasive breast adenocarcinoma characterized by the presence of distinct changes in the overlying skin. "Previous studies conveyed that NF-κβ can dramatically increase the expression of many genes in inflammatory breast cancer, including CD40, IL15, COX2, and CXCL1." (PMID 40035822, 2025).
intestinal inflammation (1 paper, 2025). "Interleukin-15 (IL-15), an inflammatory cytokine that perturbs gut microbiota equilibrium, has been shown to diminish S24-7 abundance and butyric acid levels in both the gut and feces of mice, precipitating intestinal inflammation." (PMID 40406341, 2025).
irritable bowel syndrome (1 paper, 2020). Irritable bowel syndrome (IBS) is a chronic functional condition of the lower gastrointestinal (GI) tract characterized by abdominal pain or discomfort and disordered bowel habit (diarrhea, constipation, or fluctuation between the two). "acetate and butyrate and reduction in the pro-inflammatory cytokine IL-15 upon supplementation of L. paracasei CNCM I-1572 to the irritable bowel syndrome (IBS) patients." (PMID 32819443, 2020).
Kawasaki disease (1 paper, 2022). A rare inflammatory disease characterized by an acute febrile, systemic, self-limiting, medium-vessel vasculitis primarily affecting children. "More recent data obtained by using an artificial intelligence (AI)-based approach also revealed that the host immune responses in MIS-C and in Kawasaki disease (KD) are similar and share an IL-15/IL-15RA pathway that is common to the viral pandemic (ViP)." (PMID 36010602, 2022).
keratitis (1 paper, 2023). A corneal disease that is characterized by inflammation of the cornea. "Specifically, the levels of IL1B, 1L8, and IL15 were found to be significantly decreased in genipin-treated corneas in the S. aureus (p = 0.005 for IL1B, p = 0.019 for IL8, p = 0.001 for IL15) and the P. aeruginosa (p = 0.013 for IL1B, p = 0.001 for IL8, p = 0.001 for IL15) keratitis model." (PMID 37108070, 2023).
kidney cancer (1 paper, 2012). Primary or metastatic malignant neoplasm involving the kidney. "Although IL-15 is currently being tested in clinical trials for the treatment of kidney cancer (NCT01021059 Protocol), the functions of the cytokine on normal epithelial cells as well as tumor cells remain poorly studied." (PMID 22363690, 2012). "Due to its immuno-stimulating activity in several preclinical models, the use of IL-15 could be a useful cytokine for the treatment of kidney cancers." (PMID 22363690, 2012). "In this context, IL-15, which is currently used in clinical trials for the treatment of kidney cancer (NCT01021059 Protocol) could be an useful alternative based on its immuno-activation activities." (PMID 22363690, 2012).
kidney stone (1 paper, 2025). "Five of these protein ratio pairs positively promote kidney stone development: BAIAP2/MME protein level ratio, GRPEL1/MME protein level ratio, HLAE/IL15 protein level ratio, CEACAM1/GGT1 protein level ratio and BTN2A1/IL18BP protein level ratio." (PMID 40673688, 2025).
lactic acidosis (1 paper, 2008). Metabolic acidosis characterized by the accumulation of lactate in the body. "Genes induced by lactic acidosis included: PLAUR, ERBB3, CD55, interleukin 15, CXCL16, angiogenin and MHC class I genes." (PMID 19057672, 2008).
liver dysfunction (1 paper, 2025). "Among them, the hepatocyte growth factor (HGF), a potential surrogate of liver dysfunction, and the proinflammatory interleukins IL6 and IL15 were most profoundly altered." (PMID 40242314, 2025).
Lyme disease (1 paper, 2006). Lyme disease (named after the towns in the USA where the disease was first identified) is a bacterial infection caused by Borrelia burgdorferi. "The concentrations of IL-1β, IL-1Ra, IL-6, sIL-6Rα, sgp130, and IL-15 in the serum of patients with Lyme disease were significantly higher than those in the serum ofcontrol group." (PMID 16864901, 2006).
lymphoblastic lymphoma (1 paper, 2021). A lymphoma composed of immature small to medium-sized precursor lymphoid cells (lymphoblasts). "This study demonstrates that gene-edited IL-15 CAR-T in the treatment of refractory lymphoblastic lymphoma causes mild CRS and is fully tolerated by the body." (PMID 34386015, 2021). "A phase 1 clinical trial of CD5-IL15/IL15 sushi CAR-T cells in refractory lymphoblastic lymphoma (NCT04594135) has been published." (PMID 34386015, 2021).
lymphocytic colitis (1 paper, 2025). Microscopic colitis characterized by the accumulation of lymphocytes in the colonic epithelium and lamina propria. "It has been shown that pro-inflammatory cytokines, such as TNF-α and IL-15, alter CLDN8 expression and distribution, resulting in lymphocytic colitis, which is characterized by epithelial barrier impairment, leak-flux diarrhea, and abnormal fluid absorption." (PMID 41321497, 2025).
malignant glioma (1 paper, 2023). A grade III or grade IV glioma arising from the central nervous system. "In summary, the data from this study suggest that a poxvirus genetically engineered to secrete IL-15, along with a prostaglandin synthesis inhibitor to block immunosuppression, is an effective treatment for increasing survival in mice with a malignant glioma." (PMID 38002466, 2023). "Cytokines such as IL-2 and IL-15 are beginning to find a role in the management of patients with malignant gliomas." (PMID 38002466, 2023).
migraines (1 paper, 2024). "Previous studies have shown that IL-15 can promote immune system activation and nociceptor sensitization in headache diseases such as migraine." (PMID 37450927, 2024). "Therefore, IL-15 can be determined as a primary mediator of the pro-inflammatory crosstalk between astrocytes and microglia in migraines." (PMID 37450927, 2024).
Myalgia (1 paper, 2026). "Multivariate models identified IL-15, IL-17A, IL-12p40, MCP-1, and MIP-1α as significant correlates of fever, rash, and myalgia." (PMID 42198752, 2026).
myasthenia gravis (1 paper, 2018). Myasthenia gravis (MG) is a rare, clinically heterogeneous, autoimmune disorder of the neuromuscular junction characterized by fatigable weakness of voluntary muscles. "miR-15b wasdown-regulated in myasthenia gravis patients and was found to regulate IL-15 expression in amouse model of the disease." (PMID 30430039, 2018).
myopia (1 paper, 2024). "They reported an upregulation of IL-13 and downregulation of IL-15 in the high myopia group compared with the control group." (PMID 39597899, 2024). "However, there were different results in the levels of IL-15, a pro-inflammatory cytokine, which showed an increased level in patients with mCNV while a decreased level in patients with high myopia." (PMID 39597899, 2024).
myxoma (1 paper, 2014). A benign soft tissue neoplasm characterized by the presence of spindle and stellate cells, lobulated growth pattern, and myxoid stroma formation. "We therefore modified a viral system to deliver the fusion protein of IL15Rα-IL15, employing a myxoma virus vector with a strong safety profile." (PMID 25329832, 2014). "In addition to the delivery of IL15Rα-IL15, the myxoma construct itself may contribute to an enhanced immune response." (PMID 25329832, 2014).
nasal polyps (1 paper, 2024). "For the nine samples obtained from rCRSwNP patients, the IL-8-producing ability of PMNs isolated from nasal polyps was enhanced in response to IL-15 treatment (posttreatment IL-8 level: 3.18-fold elevations compared to the pretreatment IL-8 level) (p < 0.05)." (PMID 38790942, 2024). "Our results suggest that IL-15 within the sinonasal mucosa plays a crucial role in promoting IL-8 secretion by infiltrating PMNs in recalcitrant nasal polyps." (PMID 38790942, 2024). "In addition, we propose a novel therapeutic strategy targeting the anti-IL-15/IL-8 axis to treat CRS with nasal polyposis." (PMID 38790942, 2024). "This is the first study to demonstrate the IL-15/IL-8 axis in the pathophysiology of CRS and its possible mechanisms in the development of nasal polyps in East Asian patients." (PMID 38790942, 2024). "IL-15 may represent one of the possible underlying cytokines that facilitate IL-8 production and could serve as a potential therapeutic target in patients with recurrent CRS, especially in non-eosinophilic nasal polyps." (PMID 38790942, 2024).
nematode infection (1 paper, 2024). "The pathways including WNT/β-catenin signaling, Th1 and Th2 activation, RAR activation, NGF-stimulated transcription, IL-15 production, and IL-4, 7, 12, and 13 signaling are the top pathways that the nematode infection elicits, which could lead to eventual protection or immune evasion." (PMID 39795948, 2024).
Neurodevelopmental delay (1 paper, 2020). "By contrast, in the absence of alcohol-exposure, activation of a network including IL-2, TNF-β, IL-10, and IL-15 was associated with neurodevelopmental delay." (PMID 31992316, 2020). "Network 1 included IL-2, TNF-β, IL-10, and IL-15 and was defined as the Alcohol-Independent Delay Network, as this network was activated specifically in controls with neurodevelopmental delay." (PMID 31992316, 2020). "Children with alcohol-independent neurodevelopmental delay (C/ND) showed activation of a single network, the Alcohol-Independent Neurodevelopmental Delay Network (network 1; IL-2, IL-15, TNF-β, and IL-10)." (PMID 31992316, 2020). "Control children experiencing neurodevelopmental delay (C/ND) showed activation of what we defined as the Alcohol-Independent Delay Network (network 1) that included IL-2, TNF-β, IL-10, and IL-15." (PMID 31992316, 2020). "For controls, we found higher average levels of a subset of cytokines including IL-4, IL-1β, PlGF, GM-CSF, SAA, IL-15, TNF-β, VEGF-D, IL-12p70, Tie-2, IL-2, IL-17α, IFN-ɣ, and IL-10 in children with neurodevelopmental delay (C/ND), compared to that of their typically developing (C/TD) counterparts." (PMID 31992316, 2020). "Based on our findings, we propose that elevations in IL-2, IL-15, TNF-β, and IL-10 may represent a non-specific immune profile broadly associated with neurodevelopmental delay during childhood, rather than serving as a more specific biomarker of any one neurodevelopmental disorder." (PMID 31992316, 2020).
nodular sclerosis (1 paper, 2022). "In the group of patients presenting a nodular sclerosis subtype, the immune profile switched at relapse, with an upregulation of LGALS1 and TGFB1 and downregulation of CD163, CD274, HGF, IL15, and ICOS." (PMID 36230815, 2022).
non-alcoholic fatty liver disease (1 paper, 2024). "Development of non-alcoholic fatty liver disease was attenuated in mice deficient for IL-15 or IL-15Rα, supporting a pro-inflammatory role of IL-15 in the liver." (PMID 38919611, 2024).
nosocomial infection (1 paper, 2024). An infection acquired in a hospital or other healthcare setting. "This analysis indicated that CPT1a and NRF1 expression levels in NK cell subsets and plasma IL-15 levels are strongly associated with nosocomial infection risk." (PMID 38426112, 2024). "In this study, the data suggest that occurrence of nosocomial infection in CCI is associated with increased IL-10 and IL-15 levels in the circulation." (PMID 38426112, 2024). "In addition, the circulating levels of five cytokines, IL-10, IL-15, IL-6, IL-8, and TNF alpha, were measured for each patient, and the results showed that patients with nosocomial infection had significantly increased IL-10 levels at RCC admission." (PMID 38426112, 2024).
obese syndrome (1 paper, 2023). "A positive correlation was observed between lipid hydroperoxide (LOOH) and levels of IL-15, TNFα, insulin, total cholesterol, LDL, and triglycerides in normal-weight obese syndrome patients." (PMID 38140309, 2023).
obstructive sleep apnea syndrome (1 paper, 2020). Cessation of air flow during sleep due to upper airway obstruction. "After the analysis of the levels of pro and anti-inflammatory markers (IL-1β, IL-4, IL-6, IL-8, IL-10, Il-15, TNF-α, CRP, α1-GP) in the tonsils, we observed higher levels of markers IL-8 and IL-10 in pediatric patients with obstructive sleep apnea syndrome." (PMID 30213594, 2020). "Verify the levels of the inflammatory markers, IL-1β, IL-4, IL-6, IL-8, IL-10, IL-15, TNF-α, CRP and α1-GP, in the tonsils of children with and without obstructive sleep apnea syndrome." (PMID 30213594, 2020).
osteonecrosis (1 paper, 2020). A none disease characterized by death of bone tissue due to a lack of blood supply. "Three-dimensional (3D) pictures of the femoral head were reconstructed, which further confirmed the H&E observation that IL-15 deficiency can lead to attenuated microstructure osteonecrosis and increased BMD." (PMID 32536957, 2020). "C57BL/6 J and l15−/−mice were injected with methylprednisolone to induce wide type osteonecrosis (WT ON) and IL-15 deficiency osteonecrosis (IL-15−/− ON)." (PMID 32536957, 2020). "All of these indicate the necessity of further detailed mechanism research about IL15 in osteonecrosis." (PMID 32536957, 2020). "Our investigation not only clarifies the inhibitive effects of IL-15 deficiency on RANKL-induced osteoclast formation, but also indicates that IL15 inhibition can be utilized as a potential target for osteonecrosis in steroid-induced ONFH patients." (PMID 32536957, 2020).
osteonecrosis of the femoral head (1 paper, 2020). "Whether IL-15 is involved in the development of steroid-induced osteonecrosis of the femoral head (ONFH) is investigated." (PMID 32536957, 2020).
pancreatitis (1 paper, 2024). Inflammation of the pancreas. "Notably, multiple inflammatory mediators, i.e., IL-17, IL-6 and IL-10 as well as IL-12 and IL-15 have been shown to play a main role in the pathogenesis of pancreatitis, and their serum levels have been reported to correlate with disease severity in AP patients." (PMID 38910880, 2024).
pemphigus (1 paper, 2022). Pemphigus is a group of rare autoimmune diseases that cause blistering of the skin and mucous membranes (mouth, nose, throat, eyes, and genitals).This conditioncan occur at any age, but often strikes people in middle or older age. "TNF- α, IL-6, IL-15, IL-10, IL-12, are involved in the mechanism of pemphigus lesions formation." (PMID 36613766, 2022).
Peri-Implantitis (1 paper, 2022). An inflammatory process with loss of supporting bone in the tissues surrounding functioning DENTAL IMPLANTS. "The genera of Peptostreptococcaceae XIG-1, Treponema, Porphyromonas, and Lachnospiraceae G-8, as well as the cytokines of IL-17A, IL-6, IL-15, G-CSF, RANTES, and IL-1β were significantly higher in peri-implantitis than healthy implants." (PMID 36233685, 2022). "Additionally, cytokines of IL-15, TNF-α, and IL-1α showed comparable amounts between healthy implants and peri-implantitis (p < 0.05)." (PMID 36233685, 2022).
polyp (1 paper, 2024). A usually exophytic mass attached to the underlying tissue by a broad base or a thin stalk. "Nevertheless, baseline absolute IL-8 levels before the IL-15 challenge were significantly higher in polyp tissue samples than in peripheral blood samples from the nine rCRSwNP patients (p < 0.05)." (PMID 38790942, 2024).
pseudoexfoliation glaucoma (1 paper, 2025). "Earlier, we showed that elevated IOPs were significantly correlated with the intracameral levels of IL-5, IL-6, IL-8, IL-10, IL-15, IL-17, and CCL2 in eyes with pseudoexfoliation glaucoma." (PMID 40353220, 2025).
Pseudomonas infection (1 paper, 2016). Infections with bacteria of the genus pseudomonas. "The levels of plasma IL-6, TNF-α, IFN-γ and MIP-2 were significantly higher in infected mice and in the IL-15 SA-treated mice receiving intraperitoneal Pseudomonas infection as compared to vehicle treated infected mice." (PMID 26859674, 2016).
rectal cancer (1 paper, 2021). A primary or metastatic malignant neoplasm that affects the rectum. "Radiation was found to have differential effects on normal rectal tissue and rectal cancer tissue with increased IL-15 and CCL22 secretion following radiation from normal rectal tissue explants (p < 0.05), while no significant alterations were observed in the irradiated rectal cancer tissue." (PMID 33540635, 2021).
rectum adenocarcinoma (1 paper, 2022). An adenocarcinoma arising from the rectum. "The protein levels of IL-15 were considerably downregulated in COADREAD (colon and rectum adenocarcinoma), LUAD, BRCA, and BLCA, while it was not obvious in LGG, SKCM, THCA, and PRAD compared with corresponding normal tissues." (PMID 36467072, 2022).
Renal Dysfunction (1 paper, 2019). "Analysis of the published GES1563 dataset shows a significant downregulation of IL-15 transcript in transplants with renal dysfunction (n=5) versus well-functioning transplants with no clinical evidence of rejection (n=10) (t-test p value =0.0042)." (PMID 31360169, 2019). "Moreover, IL-15 expression is reduced in biopsies of transplanted patients with renal dysfunction without rejection in comparison of transplant patients from well-functioning transplants without rejection." (PMID 31360169, 2019).
Rett syndrome (1 paper, 2020). A severe neurodevelopmental disorder affecting the central nervous system. "Finally, while IL-15 is not a commonly measured cytokine in studies of neurodevelopmental disorders, there is evidence for elevated levels of IL-15 in Rett syndrome." (PMID 31992316, 2020).
rhabdoid tumor (1 paper, 2024). An aggressive malignant embryonal neoplasm usually occurring during childhood. "Mature cells of CD56bright CD16bright phenotype showed upregulation of CD56, CD16, and NK cell activation markers NKG2D and NKp46 upon IL-15 exposure, while exposure to aggressive atypical teratoid/rhabdoid tumor (ATRT) cell lines enhanced NKG2D and NKp46 expression." (PMID 38496035, 2024).
Rickettsiosis (1 paper, 2015). A group of infectious diseases that is caused by Rickettsia. "Elevation of serum IFNγ and IL-15 concentrations were also noted in R. parkeri-inoculated animals at 1 and 4 dpi indicating evidence of a TH1 response in these animals, which has been well described in SFG rickettsiosis." (PMID 26244337, 2015).
SARS-CoV infection (1 paper, 2020). "Interestingly, a study compared IL-15 levels from lung tissue homogenates following SARS-CoV infection in aged vs. juvenile monkeys and showed that IL-15 concentrations were only elevated in juvenile monkeys 10 days post-infection." (PMID 32655581, 2020).
Sézary syndrome (1 paper, 2016). "Both, IL-2 and IL-15 reportedly promote growth and viability of CTCL and Sézary syndrome derived cell lines, while co-expression of IL-15 and IL-17F characterizes mycoses fungoides." (PMID 27144517, 2016).
simian immunodeficiency virus infection (1 paper, 2021). An infection affecting monkeys, chimpanzees, and other non human primates caused by a HIV-like virus. "In this review, we summarize the current research on free IL-15 and N-803, an IL-15 superagonist, in the context of therapeutic interventions for treated and untreated HIV infection in humans and SIV (simian immunodeficiency virus) infection in nonhuman primates." (PMID 34578331, 2021).
sinusitis (1 paper, 2012). An acute or chronic inflammatory process affecting the mucous membranes of any sinus cavity. "One gag DNA+IL-15 DNA participant had a severe headache on day 3 following the 2nd vaccination, which was thought to be related to sinusitis, not vaccination." (PMID 22242162, 2012).